SPNS2 (SPNS lysolipid transporter 2, sphingosine-1-phosphate)
Description:
Lipid transporter that specifically mediates export of sphingosine-1-phosphate (sphing-4-enine 1-phosphate, S1P) and sphinganine-1-phosphate in the lymph, thereby playing a role in lymphocyte trafficking. S1P is a bioactive signaling molecule that regulates many physiological processes important for the development and for the immune system. Regulates levels of S1P and the S1P gradient that exists between the high circulating concentrations of S1P and low tissue levels that control lymphocyte trafficking. Required for the egress of T-cells from lymph nodes during an immune response by mediating S1P secretion, which generates a gradient that enables activated T-cells to access lymph (By similarity). Also required for the egress of immature B-cells from the bone marrow (By similarity). In contrast, not involved in S1P release from red blood cells (By similarity). Involved in auditory function. S1P release in the inner ear is required for maintenance of the endocochlear potential in the cochlea (By similarity). In addition to export, also able to mediate S1P import (By similarity).
Synonyms: SLC63A2; DFNB115; SLC62A2
Tractability: Small molecule: a structure with a bound ligand is known. Antibody: its Gene Ontology location is reachable by antibodies, with high confidence; UniProt places it where antibodies can reach, with medium confidence; UniProt predicts a signal peptide or a membrane-spanning region. PROTAC: ubiquitination databases record sites on it.
Gene: Protein-coding gene on chromosome 17 (4,498,850 to 4,539,036, forward strand). Ensembl gene ENSG00000183018.
Subcellular location: Cell membrane; Endosome membrane
Pathways (Reactome):
Metabolism: Sphingolipid de novo biosynthesis
Gene Ontology:
Molecular function: sphingolipid transporter activity; transmembrane transporter activity
Biological process: lipid transport; regulation of humoral immune response; regulation of T cell migration; sensory perception of sound; sphingolipid biosynthetic process; sphingosine-1-phosphate receptor signaling pathway; lipid translocation; transmembrane transport
Cellular component: endosome membrane; membrane; plasma membrane
Genetic constraint (gnomAD): Loss-of-function variants: 37 observed, 50.83 expected, observed/expected ratio (o/e) 0.73, 90% interval 0.56 to 0.96. The synonymous counts are far from expectation, so gnomAD's model fits this gene poorly and the ratio says little. Missense variants: 786 observed, 674.89 expected, observed/expected ratio (o/e) 1.16, 90% interval 1.1 to 1.24. Synonymous variants: 417 observed, 300.24 expected, observed/expected ratio (o/e) 1.39, 90% interval 1.28 to 1.51.
Homologues: Orthologues: macaque SPNS2 (97% identical), chimpanzee SPNS2 (96% identical), mouse Spns2 (96% identical), rat Spns2 (96% identical), guinea pig SPNS2 (95% identical), pig SPNS2 (95% identical), rabbit SPNS2 (81% identical), dog SPNS2 (79% identical), tropical clawed frog spns2 (72% identical), Drosophila melanogaster spin (39% identical), Caenorhabditis elegans spin-1 (34% identical), Caenorhabditis elegans spin-4 (33% identical), and 2 more. Paralogues in human: SPNS1 (49% identical), SPNS3 (41% identical).
Diseases named in the same sentence as SPNS2 in open-access papers:
SPNS2 is named in the same sentence as 63 diseases in open-access papers, as found by Europe PMC text mining. Sharing a sentence is not in itself a finding about the gene and the disease. The quoted sentences say what the papers report.
colorectal cancer (6 papers, 2021 to 2024). A primary or metastatic malignant neoplasm that affects the colon or rectum. "Another study of our group demonstrated that copy number loss of SPNS2 in colorectal cancer led to low expression of SPNS2, which inhibits metastasis of colorectal cancer." (PMID 38504159, 2024). "Contrastingly, low SPNS2 levels are associated with worse clinical prognosis in colorectal cancer, while the ectopic expression of SPNS2 was shown to decrease migration, invasion, and metastasis in colorectal cancer cell lines via AKT signaling pathway." (PMID 35565311, 2022). "The authors reported that the levels of SPNS2 were downregulated in colorectal cancer and were associated with poor differentiation, advanced pTNM stage and poor prognosis of the disease." (PMID 36309544, 2022). "The up-regulation or down-regulation of SPNS2 has been linked to many cancers, including acute myeloid leukemia, lung cancer, and colorectal cancer." (PMID 33673355, 2021). "Similarly to our study, the expression of Spns2 was found to be increased in some neoplasms including colorectal cancer and clear cell renal cell carcinoma." (PMID 39595959, 2024). "Collectively, these results suggested that SPNS2 might promote tumorigenesis in the early stage, but inhibit tumor progression in the late stage of CRC, and its expression is a prognostic factor for colorectal cancer." (PMID 34249729, 2021).
lung cancer (6 papers, 2014 to 2024). A malignant neoplasm involving the lung. "Downregulation of SPNS2 is a potential risk factor for non‐small cell lung cancer." (PMID 38429907, 2024). "The knockdown of SPNS2 was shown to increase intracellular S1P levels in non-small-cell human lung cancer cells, thereby promoting cell migration and inhibiting apoptosis." (PMID 33673355, 2021). "In lung cancer cells, the overexpression of SPNS2 has been shown to induce cell apoptosis, and SPNS2 knockdown enhances cell migration." (PMID 33673355, 2021). "Per our results on CF human bronchial epithelial cells, S1P accumulates in Spns2 knockdown lung cancer cells because of enhanced S1P synthesis and reduced degradation." (PMID 34572307, 2021). "In this study, we observed increased the phosphorylation levels of AKT after SPNS2 knockdown, in line with a previous study in lung cancer." (PMID 34249729, 2021). "Genetically, Spns2 mRNA level was found to be reduced in advanced lung cancer (LC) patients as quantified by using a small scale qPCR array." (PMID 25330231, 2014). "Interestingly, the expression of the specific S1P transporter, Spns2, was also reduced in advance lung cancer patients." (PMID 27800303, 2016). "As already reported in lung cancer and COPD, Spns2 expression might regulate S1P metabolism by influencing the finely tuned equilibrium between synthesizing and degrading enzymes in CF." (PMID 34572307, 2021).
breast carcinoma (5 papers, 2017 to 2024). "However, future in vitro studies are required to explore the role of SPNS2 and its association to S1P axis in breast cancer patients." (PMID 36309544, 2022). "Consistent with the findings observed in mouse models, SPNS2 has been reported to be upregulated in the stromal gene expression signature associated with a poor clinical outcome of human breast cancer, which underscores the clinical relevance of the present study." (PMID 28209174, 2017). "SPNS2 seems to function as a breast cancer suppressor, not only it can inhibit breast cancer cell migration, but high level of SPNS2 predicts good survival in different cohorts." (PMID 36285700, 2022). "In agreement with our mechanistic model, we showed that human breast cancers with a high amount of angiogenesis are significantly associated with high expression of S1P-signaling genes, SphK1, S1PR1, and SPNS2." (PMID 32933189, 2020). "Our group was the first to demonstrate the mechanism of how S1P is generated inside a breast cancer cell by SphK1, where SphK2 is often suppressed in a compensatory manner, and is then exported out of breast cancer cells by transporters including SPNS2." (PMID 32933189, 2020). "While primary tumor growth was not affected in Spns2 mutant mice, spontaneous and experimental metastasis to lung and liver was reduced when they were injected with metastatic melanoma, colorectal, or breast cancer cell lines." (PMID 28209174, 2017).
deafness (5 papers, 2014 to 2025). An inherited or acquired condition characterized by the complete loss of the ability to hear from one or both ears. "A somewhat similar approach has been used to reverse the effects of the Spns2 mutation, which causes loss of endolymphatic potential and deafness." (PMID 40100636, 2025). "Our finding of reversal of hearing loss in individual mice after activation of the Spns2 gene is an important proof of concept that deafness associated with EP deficiency not only can be halted in its progression but also can be reversed." (PMID 37552762, 2023). "Spns2-deficient mice showed early onset of hearing loss that progressed rapidly to profound deafness." (PMID 25356849, 2014). "However, the eye defects were of particular interest because of the relatively common association of retinal defects with deafness, as in Usher syndrome for example, and our finding of Spns2 expression in the eye." (PMID 25356849, 2014). "The human version of this gene, SPNS2, may be involved in human deafness, and understanding the underlying mechanism presents an opportunity to develop potential treatments for this form of hearing loss." (PMID 25356849, 2014). "Taken together, these findings suggest that SPNS2 is not only a candidate gene for involvement in deafness, but also for deaf-blind syndromes." (PMID 25356849, 2014). "Our findings suggest that Spns2 is a promising candidate gene for human deafness." (PMID 25356849, 2014). "Without the normal function of the Spns2 gene and release of sphingosine-1-phosphate locally in the inner ear, the voltage in the cochlea declines, leading to rapid loss of sensitivity to sound and ultimately to complete deafness." (PMID 25356849, 2014).
lymphopenia (5 papers, 2012 to 2024). Reduction in the number of lymphocytes. "SPNS2-deficient mice exhibit peripheral lymphopenia and defects in B cell homing to secondary lymphoid organs, which results in impaired humoral immunity upon immunization with E. coli and suggests SPNS2 as a target for immunosuppressive therapy." (PMID 35163211, 2022). "SPNS2-deficient mice displayed reduced circulating S1P levels coupled with lymphopenia." (PMID 35163211, 2022). "Genetic inhibition of Spns2 results in lymphopenia, which protects the animals from various inflammatory conditions, highlighting its potential as a druggable target." (PMID 33334894, 2021). "Despite the lymphopenia seen in the SPNS2 knock-out mice, the level of natural killer cells in the lungs was increased, together with the T cell activities of CD4+ and CD8+ T cells, which all contribute to reduced metastasis." (PMID 31330821, 2019). "Indeed, when lymphocyte counts were measured at 4 h,a maximum level of lymphopenia (∼50%) was observed, which issimilar to Spns2 knock out mice." (PMID 38952222, 2024). "Interestingly, SPNS2 systemic or endothelial cell-specific knock-out lead to lymphopenia, in contrast to the Mfsd2b knock-out, which results in a similar decrease in plasma S1P." (PMID 31330821, 2019). "In addition to lymphopenia, SPNS2-deficient mice show an EOB phenotype, suggestingthat SPNS2 also functions in cells other than the vascular ECs." (PMID 22723910, 2012). "These long-term effects are probably underestimated in studies where, e.g., short-term experimental metastasis models are not affected by lymphopenia upon SPNS2 ablation or SGPL1 inhibition." (PMID 35163211, 2022).
autoimmune disease (4 papers, 2018 to 2024). A disorder resulting from loss of function or tissue destruction of an organ or multiple organs, arising from humoral or cellular immune responses of the individual to their own tissue constituents. "Mainly the fact that blood S1P levels are reduced by 40% in Spns2-deficient mice and that these mice are lymphopenic suggests that T lymphocyte-driven inflammatory and autoimmune diseases can in principle be reduced by Spns2 downregulation or inhibition." (PMID 29772789, 2018). "FTY720, a functional antagonist of S1PR1 that is used extensively to treat patients with autoimmune disease, induces naive T cell death via the same pathway as genetic deletion of SPNS2 and S1PR1." (PMID 38194271, 2024). "The top SNV of the CFA5 locus was located in an intron of the sphingolipid transporter 3 (SPNS3) gene for which the paralogous gene (SPNS2) is known to be important in immunological development, and inflammatory and autoimmune diseases." (PMID 33793571, 2021). "In mice, Spns2 plays a critical role in inflammatory and autoimmune diseases, wherein Spns2 deletion appears to have a strong effect in alleviating the development of collagen-induced arthritis." (PMID 33673355, 2021).
colitis (4 papers, 2017 to 2024). Inflammation of the colon. "Indeed, it was recently shown that Spns2-deficient mice are protected in an airway inflammation and hypersensitivity model as well as in models of colitis, arthritis, and experimental autoimmune encephalomyelitis." (PMID 29772789, 2018). "The Spinster homologue 2 (Spns2) transporter passively exports S1P from vascular endothelial cells and Spns2 knockout mice are protected from airway inflammation, colitis, arthritis and experimental autoimmune encephalopathy (EAE)." (PMID 28241498, 2017). "Relevant for our study, mice deficient for Spns2 (Spinster homologue 2) exhibit reduced disease severity in several inflammation and autoimmune mouse models, such as experimental autoimmune encephalomyelitis, CIA, colitis, or airway inflammation." (PMID 33861848, 2021).
non-small cell lung carcinoma (4 papers, 2016 to 2020). A group of at least three distinct histological types of lung cancer, including non-small cell squamous cell carcinoma, adenocarcinoma, and large cell carcinoma. "Spns2 has been implicated in a variety of physiologic and pathologic processes, including hyperoxia-induced lung damage, airway inflammation and hypersensitivity and non-small cell lung cancer." (PMID 29112690, 2017). "In a first study, SPNS2 was downregulated in a small cohort of human lung tumors and overexpression of SPNS2 in non-small cell lung carcinoma cells led to increased S1P secretion, decreased cell migration, and induction of apoptosis." (PMID 31330821, 2019). "On the contrary, over expression of Spns2 induced apoptosis in non-small cell lung cancer (NSCLC) cells." (PMID 27800303, 2016). "For example, previous study found that knockout SPNS2 gene can worsen non-small cell lung cancer 16, another research illustrated SPNS2 may play a role in inhibiting the development and progression of gastric cancer." (PMID 32489475, 2020).
hearing loss (3 papers, 2014 to 2025). "The pattern of reduced EP and altered strial morphology early in the progression of the hearing loss is very similar to that seen in mice with a mutation of Spns2, another component of S1P signalling." (PMID 27383011, 2016). "In summary, we report here that Spns2-deficient mice displayed rapidly progressive hearing impairment associated with a rapid decline in the EP between P14 and P21." (PMID 25356849, 2014). "Finally, coupling our structural results and protein localization, our results explain the pathogenic effects of SPNS2 mutations implicated in hearing loss." (PMID 39820269, 2025). "Based on the modest activity of the D163N mutant, we hypothesize there is a minimal S1P export activity needed from SPNS2 for proper development of the stria vascularis, below which it becomes disorganized and thereby leads to hearing loss." (PMID 39820269, 2025). "This indicates that Spns2-deficient and Pds-deficient mice may have different mechanisms underlying the reduced EP and hearing impairment." (PMID 25356849, 2014).
liver fibrosis (3 papers, 2016 to 2018). "It should be further elucidated whether enhanced expression of SPNS2 in liver might be simply associated with liver fibrosis or importantly involved in its mechanism." (PMID 27562371, 2016). "S1P may be transported out of cells by Spns2 in the process of liver fibrosis, and then combines with S1PR to promote the liver fibrosis." (PMID 30687087, 2018). "This upregulated Spns2 in liver fibrosis may result in enhanced S1P secretion and enhanced autocrine or paracrine action via S1P receptors to stimulate the fibrotic process." (PMID 29772789, 2018). "In addition, the effect of intracellular S1P in liver fibrosis is closely related to the role of transporter Spns2." (PMID 30687087, 2018). "Thus, a role of SPNS2 in liver fibrosis should be further elucidated." (PMID 27562371, 2016). "In conclusion, our study, using human liver tissue samples, shows that increased activity of SK1/S1P pathway, S1P secretion via SPNS2, and S1P binding to S1P2 may play an important role in the progression of liver fibrosis with recruitment of inflammatory cells." (PMID 27562371, 2016).
Sepsis (3 papers, 2021 to 2024). Sepsis is defined as life-threatening organ dysfunction caused by a dysregulated host response to infection. "Recent molecular studies have highlighted the role of the Spns2/S1P signaling pathway in regulating lung-specific immune responses during sepsis." (PMID 39594987, 2024). "This organ-specific modulation of immune responses suggests that targeting the Spns2/S1P axis could be a viable strategy for treating ARDS in sepsis patients." (PMID 39594987, 2024). "Consequently, enhancing Spns2/S1P signaling helps balance the inflammatory imbalance and immune response during sepsis." (PMID 38482014, 2024).
Breast invasive carcinoma (2 papers, 2021 to 2022). "Similar to our findings, a recent study suggests that SPNS2 expression was markedly lower in ten kinds of tumor (including breast invasive carcinoma) as compared to adjacent non-cancerous samples." (PMID 36309544, 2022). "SPNS2 expression was markedly lower in ten kinds of tumor compared to the adjacent noncancerous samples, such as BRCA (Breast invasive carcinoma), LIHC (Liver hepatocellular carcinoma), LUAD (Lung adenocarcinoma) and LUSC (Lung squamous cell carcinoma)." (PMID 34249729, 2021).
colon cancer (2 papers, 2020 to 2021). "By regulating the phosphorylation of the serine/threonine protein kinase (AKT) and the signal-regulated kinase (ERK) pathways, it appears that SPNS2 enhances the malignancy of colon cancer in terms of cell proliferation, migration, and invasion as well as inhibits apoptosis." (PMID 33673355, 2021). "In colon cancer cells, SPNS2 has been found to activate the AKT and ERK pathways." (PMID 33673355, 2021). "Overexpression of Spns2 is believed to initiate compensatory mechanism by which colon cancer cells restore S1P levels by upregulating SphK1 and SphK2 and activate ERK and AKT signaling pathways that are by all means important for cell survival and cancer progression." (PMID 32456134, 2020). "Little is known about the Spns2 regulation in colon cancer, but findings from the studies in other cancer types such as cervix adenocarcinoma underline the importance of Spns2-induced S1P secretion for promotion of cancer cell invasion in response to EGF signaling." (PMID 32456134, 2020). "It has been documented that Spns2 mRNA and protein levels are highly expressed in colon cancer tissues in comparison with adjacent non-cancerous tissues and to correlate with tumor size, which points to the role of Spns2 in colon cancer progression." (PMID 32456134, 2020).
multiple sclerosis (2 papers, 2023 to 2025). A progressive autoimmune disorder affecting the central nervous system resulting in demyelination. "In addition, deletion of SPNS2 prevented disease development in a mouse model of multiple sclerosis, indicating that SPNS2 is a promising new drug target for treating multiple sclerosis." (PMID 37499662, 2023). "A more favorable approach for treating multiple sclerosis may be to interfere with the S1P signaling upstream of S1P receptors, for example by reducing S1P release through the inhibition of SPNS2 transport activity." (PMID 37499662, 2023). "SPNS2 also exports the S1P-mimicking FTY720-P (Fingolimod) and thereby is central to the pharmacokinetics of this drug when treating multiple sclerosis." (PMID 39820269, 2025).